RDH16 (retinol dehydrogenase 16)
Description:
Oxidoreductase with a preference for NAD. Oxidizes all-trans-retinol, 9-cis-retinol, 11-cis-retinol and 13-cis-retinol to the corresponding aldehydes. Has higher activity towards CRBP-bound retinol than with free retinol. Also oxidizes 3-alpha-hydroxysteroids. Oxidizes androstanediol and androsterone to dihydrotestosterone and androstanedione. Can also catalyze the reverse reaction.
Synonyms: hRDH-E; RoDH-4; RODH4; SDR9C8
Tractability: Antibody: UniProt predicts a signal peptide or a membrane-spanning region. PROTAC: ubiquitination databases record sites on it.
Gene: Protein-coding gene on chromosome 12 (56,950,087 to 56,959,374, reverse strand). Ensembl gene ENSG00000139547.
Subcellular location: Microsome membrane; Endoplasmic reticulum membrane
Pathways (Reactome):
Sensory Perception: The canonical retinoid cycle in rods (twilight vision)
Signal Transduction: RA biosynthesis pathway
Gene Ontology:
Molecular function: all-trans-retinol dehydrogenase (NAD+) activity; androstan-3-alpha,17-beta-diol dehydrogenase (NAD+) activity; androsterone dehydrogenase [NAD(P)+] activity; electron transfer activity; identical protein binding; 11-cis-retinol dehydrogenase (NAD+) activity; alcohol dehydrogenase (NAD+) activity; oxidoreductase activity, acting on the CH-OH group of donors, NAD or NADP as acceptor
Biological process: steroid metabolic process; lipid metabolic process; retinol metabolic process
Cellular component: intracellular membrane-bounded organelle; endoplasmic reticulum membrane
Genetic constraint (gnomAD): Loss-of-function variants: 25 observed, 23.8 expected, observed/expected ratio (o/e) 1.05, 90% interval 0.76 to 1.47. The upper end of that interval is the gene's LOEUF score, 1.47, which puts it in group 6 of 6, group 1 being the genes least tolerant of losing a copy. Missense variants: 413 observed, 416.47 expected, observed/expected ratio (o/e) 0.99, 90% interval 0.91 to 1.08. Synonymous variants: 154 observed, 173.83 expected, observed/expected ratio (o/e) 0.89, 90% interval 0.78 to 1.01.
Homologues: Orthologues: chimpanzee RDH16 (99% identical), macaque RDH16 (94% identical), dog RDH16 (77% identical), pig RDH16 (77% identical), guinea pig RDH16 (76% identical), mouse Rdh1 (74% identical), mouse Rdh16 (73% identical), mouse Rdh7 (73% identical), rat Rdh7 (72% identical), mouse Rdh9 (72% identical), rat LOC120093075 (71% identical), mouse Rdh19 (71% identical), and 6 more. Paralogues in human: HSD17B6 (66% identical), RDH5 (52% identical), SDR9C7 (51% identical), DHRS9 (47% identical), BDH1 (38% identical), HSD17B2 (34% identical), HSD11B2 (32% identical), HSD17B1 (26% identical), RDH12 (26% identical), RDH11 (25% identical), DHRS3 (23% identical), SDR16C5 (23% identical), and 13 more.
Diseases named in the same sentence as RDH16 in open-access papers:
RDH16 is named in the same sentence as 13 diseases in open-access papers, as found by Europe PMC text mining. Sharing a sentence is not in itself a finding about the gene and the disease. The quoted sentences say what the papers report.
breast carcinoma (5 papers, 2020 to 2023). "RDH16 is also associated with the prognosis of breast cancer and cholangiocarcinoma." (PMID 38057871, 2023). "RDH16 affects retinol metabolism to participate indirectly in breast cancer occurrence and progression." (PMID 37303949, 2023). "While there are few studies on RDH16 in breast cancer, RDH16 has been shown to mainly affect retinol metabolism to participate indirectly in breast cancer occurrence and progression." (PMID 32322168, 2020).
glioma (2 papers, 2021 to 2022). A benign or malignant brain and spinal cord tumor that arises from glial cells (astrocytes, oligodendrocytes, ependymal cells). "PCGF1 expression is increased in oral squamous cell carcinoma stem cells and promotes glioma stem cell self-renewal by downregulating the expression of RDH16." (PMID 34148069, 2021). "PCGF1 also promoted self-renewal of glioma stem cells by downregulating the expression of RDH16." (PMID 34148069, 2021).
cholestasis (1 paper, 2023). Impairment of the bile flow caused by obstruction within the liver, or outside the liver in the bile duct system. "The genes regulated in all pathways, Cyp1a1, Cyp1a2, Cyp2a1, Cyp2b1, Cyp4a8, Cyp2c11, Rdh16, Alox15, Ephx2, Sult2a1, and Acox2, were the potential targets for ZYP treatment of cholestasis." (PMID 37881184, 2023).
COVID-19 (1 paper, 2024). A disease caused by infection with severe acute respiratory syndrome coronavirus 2. "IVW analysis showed RDH16 was associated with increased COVID-19 hospitalization (OR: 1.10, 95% CI: 1.01–1.18, P: 0.0199)." (PMID 38671384, 2024). "IVW analysis showed a positive causal association between RDH16 and COVID-19 hospitalization (OR: 1.10, 95% CI: 1.01–1.18, P: 0.0199) using a liberal selection of genetic variants (P < 5 × 10− 6)." (PMID 38671384, 2024). "In our MR study, the positive association between RDH16 with COVID-19 hospitalization were also found, which requires further confirmation by future research." (PMID 38671384, 2024). "In the present study, based on the available GWAS, we investigate the causal effect of COVID-19 and retinol, RBP4, RDH16 and CRABP1 through two-sample MR approach." (PMID 38671384, 2024). "We found evidence of possible causal association of retinol, RBP4, RDH16 and CRABP1 with the susceptibility, hospitalization and severity of COVID-19." (PMID 38671384, 2024). "We conducted a two-sample Mendelian randomization (MR) study to assess the associations of retinol, retinol binding protein 4 (RBP4), retinol dehydrogenase 16 (RDH16) and cellular retinoic acid binding protein 1 (CRABP1) with COVID-19 in European population." (PMID 38671384, 2024). "Here, we assessed the association between the development and severity of COVID-19, and retinol and RA signaling pathway, by MR, utilizing alleles as proxies for the genetically predicted circulating status of retinol, RBP4, RDH16 and CRABP1." (PMID 38671384, 2024). "However, no causal effect of RDH16 on COVID-19 severity (OR: 1.12, 95% CI: 0.99–1.26, P: 0.0562) was detected." (PMID 38671384, 2024).
hepatocellular carcinoma (1 paper, 2026). A malignant tumor that arises from hepatocytes. "Firstly, RDH16 expression is significantly downregulated in hepatocellular carcinoma, correlating with poor patient prognosis, suggesting a tumor-suppressive function." (PMID 41601632, 2026).
liver cancer (1 paper, 2026). An epithelial or non-epithelial malignant neoplasm that arises from the liver. "In Dataset 2, the inverse variance weighted method again yielded a significant result (OR = 0.752, 95% CI: 0.642-0.880, P < 0.001), further supporting a protective role of RDH16 in liver cancer risk." (PMID 41601632, 2026). "We conducted MR analysis using two independent datasets to assess the causal relationship between RDH16 and the risk of liver cancer." (PMID 41601632, 2026). "In conclusion, using the inverse variance weighted method, both independent datasets demonstrated a significant inverse correlation between RDH16 and liver cancer risk." (PMID 41601632, 2026). "In Dataset 1, the inverse variance weighted method revealed an odds ratio (OR) of 0.825 (95% CI: 0.696-0.977, P = 0.026), suggesting a protective effect of RDH16 against liver cancer." (PMID 41601632, 2026). "While results from other MR methods varied, the overall trend consistently indicated that RDH16 may exert a protective role in liver cancer development." (PMID 41601632, 2026).
sarcoma (1 paper, 2021). A usually aggressive malignant neoplasm of the soft tissue or bone. "Interestingly, the G2 subgroup mainly contained the sarcomas with elevated expression of RDH11, RDH8, RDH16, CYP2A6, and ALDH1A2, all of them were strongly or slightly correlated with poor survival." (PMID 35186946, 2021).
cancer (7 papers, 2020 to 2026). A tumor composed of atypical neoplastic, often pleomorphic cells that invade other tissues. "Similarly, a 4-gene (TOP2A, SLC22A1, PDZK1IP1, RDH16) combination for predicting cancer recurrence was selected." (PMID 35422802, 2022). "Among them, ENSR00000052553 is the cancer-type-specific eRNA of HCC, which regulates the expression of SUOX and RDH16, and can be considered as a potential target eRNA for further treatment studies of HCC." (PMID 35646665, 2022).
tumor (5 papers, 2015 to 2026). "RDH16 expression was significantly reduced in HCC tissues compared with non-tumor liver tissues and was associated with vascular invasion, elevated alpha-fetoprotein levels, poor tumor differentiation, and advanced T stage." (PMID 41601632, 2026). "Concurrently, it examines the function of RDH16 within tumor cells and its association with the immune microenvironment of HCC, with the objective of identifying novel molecular markers for HCC treatment." (PMID 41601632, 2026). "The level of RDH16 expression is inversely associated with tumor size, microsatellite formation, thrombus and OS in HCC patients." (PMID 32514252, 2020). "Research indicates that RDH16 inhibits tumor cell growth and migration by increasing retinoic acid levels and blocking fatty acid synthesis, which is potentially linked to M2 macrophage polarization, which typically exhibits pro-tumor properties in the tumor microenvironment." (PMID 41601632, 2026). "In addition, given the close association between RDH16 and the remodeling of the tumor immune microenvironment, RDH16 may influence the efficacy of immune checkpoint inhibitor therapy." (PMID 41601632, 2026). "The corresponding multiplex immunofluorescence results for CD163 and CD3 in RDH16-high and RDH16-low tumor regions are presented." (PMID 41601632, 2026). "Using single-cell analysis, this study uncovers a novel role for RDH16 in regulating tumor immune infiltration, particularly in promoting M2 macrophage and suppressive T cell infiltration." (PMID 41601632, 2026). "Clustering analysis revealed that RDH16 was primarily expressed in normal hepatocytes and malignant tumor cells within the tumor microenvironment." (PMID 41601632, 2026). "Immunohistochemical analysis of normal (N) and tumor (T) liver tissues shows that RDH16 exhibits brownish-yellow granular cytoplasmic staining in normal hepatocytes, with expression levels significantly higher than in HCC tissues." (PMID 41601632, 2026). "The results showed that CDCA8 was highly expressed and RDH16 was lowly expressed in HCC tumor tissues." (PMID 38057871, 2023). "RDH16 is a tumor-suppressing gene, and it had been reported that downregulation of RDH16 occurs in approximately 90% of primary HCC patients with poor prognosis." (PMID 35646665, 2022). "In contrast, tumor regions showed relatively low levels of RDH16 expression." (PMID 41601632, 2026). "However, high RDH16 expression in normal liver tissue correlates with CD3+ lymphocyte infiltration, while its absence in tumor regions negatively correlates with CD163+ histiocytic infiltration." (PMID 41601632, 2026). "Functional assays indicated that RDH16 did not directly affect tumor cell proliferation, migration, or invasion." (PMID 41601632, 2026). "Notably, RDH16 expression was inversely correlated with infiltration of CD163+ M2 macrophages, suggesting a potential immunomodulatory role in the tumor microenvironment." (PMID 41601632, 2026). "Critically, overexpression of RDH16 does not directly affect tumor cell proliferation, migration, or invasion." (PMID 41601632, 2026). "In contrast, the absence of RDH16 may promote M2 macrophage infiltration, which is detrimental to the tumor immune response." (PMID 41601632, 2026).
RDH16 also shares sentences with these, for which no sentence is quoted: cholangiocarcinoma (1 paper); Hepatic fibrosis (1); malignant glioma (1); metabolic syndrome (1).